DPP4 (dipeptidyl peptidase 4)
Diseases named in the same sentence as DPP4 in open-access papers (continued):
Sharing a sentence is not in itself a finding about the gene and the disease.
tumor (continued). "Although limiting growth tumour progression in a mouse model, anti-DPP4-4-1BB CAR-T cells exhibited self-antigen-driven fratricide, indicating that a more optimized design or alternative target is needed." (PMID 35158891, 2022). "We queried the association between the mRNA expression levels of DPP4/CTNNB1/MET and tumor infiltrations of immunosuppressive cells using the TCGA cohorts." (PMID 35205190, 2022). "Our differential expression analysis revealed that the (m)RNA expression levels of DPP4/CTNNB1/MET were higher in THCA tumor tissues compared with adjacent normal tissues." (PMID 35205190, 2022). "Decreased expression of DPP4 and the subsequent increase in bio-active substrate levels promote tumor cell proliferation and disease progression." (PMID 34556748, 2021). "One of the well-known tumor progression effects of DPP4 is through its catalytic activity on chemokines." (PMID 34298800, 2021). "Accordingly, in a DPP4 downregulated tumor such as LUSC, increased DNA methylation levels were observed." (PMID 33614513, 2021). "Previous work demonstrated that CXCL10, an established DPP4 substrate, mediates T-cell migration and recruitment to tumour tissue in vivo." (PMID 33513866, 2021). "DPP4 expression showed significant correlations with tumor purity in LUSC and significant correlations with the infiltration of B cells, CD8+ T cells, CD4+ T cells, macrophages, neutrophils, and dendritic cell." (PMID 33614513, 2021). "DPP4 can also exert its tumor progressive effect through induction of epithelial-mesenchymal transition (EMT) and upregulation of EMT markers such as N-cadherin, Slug, Twist, and vimentin." (PMID 34955820, 2021). "The intensities of DPP4 staining in tumor-matched controls, Gleason 3, Gleason 4 and Gleason 5 tumors were 2.51 ± 0.75, 2.69 ± 0.57, 1.96 ± 0.92 and 1.47 ± 0.92, respectively." (PMID 34556748, 2021). "By contrast to serum, where only an ~50% decrease in specific activity was detected, we observed an almost complete abrogation of tumour-specific DPP4 abundance and activity following sitagliptin treatment." (PMID 33513866, 2021). "ROC analysis defined the cut-off level of serum sCD26/DPP4 titer variation at day 29 pre/post for the clinical outcome of SD as tumor response or PFS." (PMID 33757558, 2021). "Phosphorylated PU.1 modulates downstream regulatory elements to activate effector genes such as DPP4, which promotes tumor growth." (PMID 34378358, 2021). "We also evaluated the effect of sitagliptin on DPP4 expression and activity in tumour tissues in situ." (PMID 33513866, 2021). "It has been shown that DPP4 participates in tumor growth and invasion and is dependent on its interactive functions with other key molecules and its enzymatic effects." (PMID 34955820, 2021). "In another analysis, the characterization of CD26− lymphocyte subsets and those with an intermediate (CD26int) and high (CD26hi) CD26/DPP4 expression revealed striking differences in anti-tumor properties." (PMID 34885056, 2021). "Here, CD26/DPP4 was detected on plasma exosomes of head and neck squamous carcinoma patients that were derived from both tumor cells and T cells." (PMID 34885056, 2021). "To investigate how DPP4 regulates tumor development, we used CRISPR/Cas9 with two independent guide RNAs (gRNAs) to knock out DPP4 in HT29 and two of the PDX cell lines, CRC57 and CRC247." (PMID 34378358, 2021). "Previous preclinical studies reported that DPP-4 suppression would impact tumor progression processes." (PMID 34063285, 2021). "The remaining 16 genes were highly expressed in tumor tissues of LUAD patients, and most of them (14/16) were identified as risk factors for LUAD patients, except for DPP4 and GDF15." (PMID 34307361, 2021). "ARV p17 was found to exert its antiangiogenic activity by upregulating transcription and release of the well-known tumor suppressor molecule dipeptidyl peptidase 4 (DPP4)." (PMID 33525607, 2021).
tumor (continued). "DPP4 is an epithelial membrane-bound serine protease, which can target numerous growth factor/cytokine signaling pathways; it also has oncogenic or tumor suppressor properties." (PMID 34556748, 2021). "DPP4 has been studied as a tumor biomarker due to its expression in various primary tumors and metastases." (PMID 34055551, 2021). "Unlike sDPP4 in circulation, there was a decreasing trend in DPP4 abundance in tumour tissue two weeks following the commencement of sitagliptin treatment." (PMID 33513866, 2021). "Dipeptidyl peptidase 4 (CD26)(+) CRCSCs enriched from CD133(+)/CD44(+) cells drive tumor metastasis." (PMID 33917482, 2021). "In contrast, DPP4 inhibition enhanced tumor rejection by preserving the full-length biologically active form of CXCL10, leading to increased trafficking of CXCR3+ cells into the TME." (PMID 33757558, 2021). "Data in previous studies suggest that DPP-4i potentially acts as either a tumor suppressor or promoter depending on the level of DPP-4/CD26 expression and its interaction in the tumor microenvironment." (PMID 36860286, 2021). "Beckenkamp considered that DPP4 can inhibit tumor metastasis through its enzymatic activity via cleaving and inactivating stromal cell derived factor-1 (SDF-1)." (PMID 34955820, 2021). "Nevertheless, CD26/DPP4 has been clearly implicated in the modulation of T-cell activation, proliferation, and effector function and CD26+ T cells are characterized by remarkable anti-tumor properties with respect to cytotoxic and migratory properties." (PMID 34885056, 2021). "Several studies have examined DPP4 expression in various malignancies to determine the role of DPP4 in tumor progression." (PMID 34955820, 2021). "In this review, we primarily focus on the possible undesirable effect of DPP-4 inhibition on tumor biology." (PMID 34063285, 2021). "The apparent cancer-specific incidence of DPP4 inactivation thus suggests the potential of inhibiting DPP4 in tailored therapeutic interventions to improve anti-tumour immunity." (PMID 33143089, 2020). "PDX HCC tissues with low DPP4 expression (n=17) had more rapid tumor growth than PDX HCC tissues with high DPP4 expression (n=7)." (PMID 32294701, 2020). "Our discovery of the uncoupling of DPP4 expression from enzyme activity in cancer cells provides a plausible explanation for this previously unclear role of DPP4 in various tumours, including ovarian, colorectal, and potentially other cancers." (PMID 33143089, 2020). "The results uncovered in the current study suggested that MCM3AP-AS1 promoted tumor inflammation and angiogenesis of ccRCC by regulating DPP4." (PMID 32714856, 2020). "In our studies, DOX suppressed tumor growth in both control and DPP-4-kd 4T1 tumors, but DOX-mediated suppression was less trend in DPP-4-kd 4T1 tumors (tumor weight (g) suppression rate (%): control 42.8% vs. DPP-4-kd 29.7%), but not yet significant." (PMID 31991851, 2020). "Briefly, low levels of DPP4 activity or sCD26 were observed in autoimmunity and immunosuppressed conditions including certain tumours, whereas high levels occur in other tumours, and also in infectious, inflammatory, and liver diseases." (PMID 32051696, 2020). "RT-qPCR and Western blot results further revealed that the expression of DPP4 was higher in ccRCC tumor tissues or Caki-1 cells (p < 0.05) at both mRNA and protein levels." (PMID 32714856, 2020). "Overall, the current study proved that MCM3AP-AS1 promoted tumor inflammation and angiogenesis of ccRCC by regulating DPP4." (PMID 32714856, 2020). "Chip-seq and luciferase reporter assays showed that circMET overexpression induced an immunosuppressive tumor microenvironment via the miR-30-5p/Snail/ DPP4/CXCL10 axis." (PMID 32430013, 2020). "A patient-derived xenograft (PDX) model was utilized to examine the correlation among DPP4 expression and tumor growth in vivo." (PMID 32294701, 2020).
tumor (continued). "Certain types of DPP-4 inhibitors are also known to show anti-tumor effects in a xenograft model via immune cells." (PMID 31969650, 2020). "C-X-C motif chemokine 12 (CXCL12), the substrate of DPP-4, and its receptor CXCR4 have been associated with the biology of cancer, such as tumor proliferation, survival, invasion and angiogenesis." (PMID 31991851, 2020). "The strong expression of DPP4 in cancer tissues, together with high expression in cancer cells derived from poorly oxygenated ascites fluid, suggests that the tumour microenvironment can exert a distinct influence on DPP4 expression and function in vivo." (PMID 33143089, 2020). "DPP4 regulates activities of various biomolecules such as cytokines and chemokines hence showing a dual roles as both tumor suppressor and activator in various cancers." (PMID 32552834, 2020). "Thirdly, the effect of DPP-4 inhibitors on the tumor response was difficult to evaluate because patients in this study included a variety types of cancer with different stages." (PMID 32084231, 2020). "Dipeptidyl peptidase 4 (DPP4) is a cell surface protein that can act as a tumor suppressor or activator, depending upon the level of expression and interaction with the microenvironment and chemokines." (PMID 31124302, 2019). "Various preclinical or in‐vivo studies have shown the role of DPP4/CD26 in either suppressing or activating tumor cells." (PMID 31124302, 2019). "The inhibition of DPP4 was found to improve both naturally occurring tumor immunity and immunotherapy by enhancing lymphocyte trafficking." (PMID 31097021, 2019). "It has been suggested that T-lymphocytes are the major source of plasma DPP4, and the development of tumor-specific T-cell tolerance will decrease the serum DPP4 level." (PMID 27936466, 2017). "They concluded that presence of DPP4 would repress CXCR3-mediated anti-tumor immunity and thus limited the infiltration of T lymphocytes." (PMID 27936466, 2017). "A recent investigation revealed that knockdown of Nrf2 attenuated naturally occurring tumor metastasis as well as metastasis induced by hypoglycemic dipeptidyl peptidase-4 inhibitors." (PMID 28402268, 2017). "It is likely that DPP4 regulate the tumor cell growth through generation of chemokines and cytokines, such as IL-6R." (PMID 27936466, 2017). "Evidence shows that DPP4 plays important roles in regulating tumor cell adhesion, invasion, and cell cycle arrest." (PMID 27936466, 2017). "In the future study, we will continue to provide more clear evidence of role for DPP4 in tumor biology and its likely interaction with the tumor microenvironment." (PMID 28060721, 2017). "Overexpression of DPP4 in UTUC correlated with higher tumor pT stage (p < 0.001), presence of nodal metastasis (p < 0.001), high histological grade (p = 0.019), vascular invasion (p < 0.001) and frequent mitosis (p = 0.003)." (PMID 27936466, 2017). "Overexpression of DPP4 promotes tumor cell growth, proliferation, and enhance cell migration and invasion." (PMID 27936466, 2017). "In conclusion, we observed that overexpression of DPP4 in UC correlated with destructive tumor behavior." (PMID 27936466, 2017). "The N‐terminal truncation of CXCL10 by DPP4 results in the generation of an antagonist form of the chemokine that limits T‐cell and NK cell migration toward infectious or tumor sites." (PMID 27137491, 2016). "DPP4 mRNA expression showed a similar pattern, with higher levels in both neoplasms than in the non tumor tissue (Kruskal-Wallis test, p = 0.001)." (PMID 25790122, 2015). "DPP4 is a serine protease that can modify tumor cell behavior and is a potential cancer therapeutic target." (PMID 24669769, 2014). "Among these, inhibitors of dipeptidyl peptidase 4 (DPP4) have attracted attention as potential therapeutic candidates, due to their diverse biological functions in glucose metabolism, inflammation, immune regulation, and tumor biology." (PMID 42193050, 2026).
tumor (continued). "Fibroblast activation protein (FAP), a dipeptidyl peptidase 4 protein, has limited expression in normal adult tissues, but is overexpressed on CAFs in a variety of tumor stroma of many epithelial tumors and can specifically target tumor stroma." (PMID 40457405, 2025). "Therefore, DPP4 emerged as the major key gene influencing sICOSL levels in the tumor microenvironment following chemotherapy." (PMID 40708008, 2025). "Furthermore, DPP4 restoration was synergized with anti–PD-1 therapy to achieve significant tumor regression in syngeneic KL murine models." (PMID 41283988, 2025). "Based on the bioinformatics analysis, DPP4 (dipeptidyl peptidase 4) was a protective factor, suggesting that the reduction of its autoantibody may be caused by the decreased DPP4 protein in the tumor." (PMID 39949782, 2025). "Moreover, tumor regression requires the presence of DPP4-reconstituted elements, underscoring the indispensable role of these elements." (PMID 41283988, 2025). "In addition, the DPP4 activity continuously reduced along with the rise of sICOSL concentration during the whole course of tumor progression." (PMID 40708008, 2025). "pointed out that DPP-4 has tumor suppressor activity, and its inhibition may lead to uncontrolled growth of lung tissue." (PMID 40040724, 2025). "However, the combination of osimertinib and sitagliptin further reduced the overall tumor cell population and nearly halved the number of DPP4‐positive tumor cells compared to osimertinib alone." (PMID 40479551, 2025). "This speculation was confirmed in the tissue sample, and the proteome data showed that more DPP4 was enriched in the pre-chemotherapy compared with post-chemotherapy tumor tissue." (PMID 40708008, 2025). "To investigate whether the hDPP4 staining reflected hDPP4 function, we analysed DPP4 activity in fresh-frozen tumour samples from those patients of the cohort where fresh-frozen material was available (n = 33)." (PMID 40579444, 2025). "Interestingly, DPP-4 inhibition also affected other immune populations, likely due to tumor shrinkage or DPP-4 expression on other immune cells, such as T cells." (PMID 40565099, 2025). "Preclinical studies have shown that targeting DPP4 with mAbs can inhibit tumor growth." (PMID 40597436, 2025). "Interstitial fluid from tumor was enriched with sICOSL and had lower DPP4 activity." (PMID 40708008, 2025). "Additionally, ENKTL tumor cells can express DPP4, which cleaves CXCL2, CXCL9, and CXCL10, chemokines that recruit T cells and NK cells into the tumor microenvironment, depleting the number of anti-tumor effector cells." (PMID 41295262, 2025). "Dipeptidyl-peptidase IV (DPP4) inhibitors have shown potential anti-tumor properties." (PMID 41096775, 2025). "Additionally, it is recommended to examine tissue samples from various OPMLs and OSCC to assess the presence of DPP-4 and compare it with other well-established tumor biomarkers." (PMID 39390508, 2024). "Aspirin, DPP-4 inhibitors, and metformin are associated with improved outcomes, while insulin use and pre-TKI statin use are linked to an increased risk of mortality and tumor recurrence in statin users." (PMID 38254739, 2024). "It seems the tumor environment plays a role in influencing the activity and expression of DPP-4." (PMID 38611003, 2024). "Studies have shown that DPP4 modulates the T-cell mechanism and promotes tumor initiation." (PMID 38203779, 2024). "Strikingly, the combination of anti-PD1 inhibitor with the anti-DPP4 inhibitor sitagliptin in the xenograft model induced a complete tumor regression, emphasizing the improved therapeutic efficacy of ICIs when combined with inhibitors of genes targeted by HCC-specific ncRNAs." (PMID 38398157, 2024). "Recent studies have suggested that DPP4 can regulate the tumor growth." (PMID 36795572, 2023). "Furthermore, based on the CPTAC database, UCLUC analysis showed a decrease in DPP4 protein expression in OV tumor tissues." (PMID 37907650, 2023).
tumor (continued). "DPP4 acts as a tumor suppressor or oncogene, depending on the study and cancer type analyzed." (PMID 37563650, 2023). "The administration of sitagliptin, a DPP4 inhibitor (DPP4i), significantly reduced tumor volume." (PMID 37587450, 2023). "The differential anti-tumor activity of these IFN-inducible chemokines appears to depend on the penultimate amino acid sequence of the NH2-terminus of the chemokine peptide chain that is cleaved by DPP4/CD26, which is expressed in the tumor stromal tissue." (PMID 37218983, 2023). "Additionally, the differential anti-tumor activity of IFN-inducible chemokines is dependent on their sensitivity to DPP4/CD26, which cleaves the dipeptide at the NH2-terminal of the chemokines." (PMID 37218983, 2023). "Considering the immunomodulatory and antioxidant effects of DPP4 inhibitors, whether DPP4 inhibitors can potentiate the anti-tumor effect of ICIs in NSCLC remains unclear." (PMID 37115489, 2023). "In fact, DPP4 inhibitors are considered to inhibit tumor development in some tumors." (PMID 36508088, 2023). "DPP4 (CD26) is a cell surface protein that affects tumour biology and immune system regulation." (PMID 37849388, 2023). "Taken together, these clinical data and in vitro cell studies imply that DPP4 may play a tumour‐suppressive role in the progression of PCa, and DPP4 SNPs might affect PCa progression through influencing DPP4 expression." (PMID 37533175, 2023). "As a result, targeting the DPP4 enzyme family could be a unique and effective strategy for promoting anti-tumor immunity in HCC." (PMID 38022651, 2023). "The expressions of DPP4 mRNA and protein were decreased in OV tumor tissues." (PMID 37907650, 2023). "Therefore, the difference in the anti-tumor effect of the IFN-inducible chemokines examined in this study is thought to be due to the difference in sensitivity to DPP4." (PMID 37218983, 2023). "Dipeptidyl peptidase IV (DPP4) has recently been regarded as a new tumor stemness-related protein." (PMID 35619895, 2022). "This demonstrated that THCA with highly expressed DPP4 was probably an immunoactive tumor that could benefit from immunotherapy." (PMID 36467461, 2022). "However, DPP4 is a tumor suppressor in nonsmall cell lung cancer, ovarian cancer, endometrial cancer, and prostatic cancer." (PMID 36467461, 2022). "Consequently, the altered expression and/or activity of DPP-4 result in the disturbance of several pathological processes, including inflammation, viral entry, immune-mediated diseases, and tumor development." (PMID 35933633, 2022). "However, DPP4 displays an antioncogenic function in those tumors linked to the CXCL12/CXCR4 axis, which is known to support neovascularization, tumor growth and metastasis during cancer development." (PMID 33525607, 2021). "Moreover, reduction of DPP4 activity using sitagliptin can protect the biological activity of CXCL10 to enhance T-cell recruitment into tumours and improve overall survival." (PMID 33513866, 2021). "DPP4 is a multifunctional protein, which possesses the capability, through its intrinsic peptidase activity, to inactivate or degrade many substrates, including chemokines involved in cell migration and tumor metastases." (PMID 33525607, 2021). "Furthermore, CD26/DPP4 can bind extracellular matrix proteins such as collagen and fibronectin, which facilitate tumor invasion." (PMID 34055551, 2021). "Redox balance plays an intricate role in cancer biology; DPP-4 inhibitors could also influence the tumor progression both favorably and unfavorably according to conditions." (PMID 34063285, 2021). "Furthermore, inhibition of DPP4 reveals IL-33-dependent eosinophil-mediated control of tumor growth." (PMID 33614513, 2021). "Although DPP-4/CD26 has been recognized as both a suppressor and inducer in tumor biology due to its various functions, how DPP-4 inhibitor affects cancer progression in diabetic patients is still unknown." (PMID 34063285, 2021).